XCL1 (X-C motif chemokine ligand 1)
Diseases named in the same sentence as XCL1 in open-access papers (continued):
Sharing a sentence is not in itself a finding about the gene and the disease.
tumor (continued). "Especially, Smerdou and group have demonstrated that rSFV-particles expressing IL-12 or a combination of XCL1 and Flt3L can induce strong T cell-dependent anticancer activity in murine tumor models, which could be further enhanced by immune-checkpoint blockade." (PMID 38425844, 2024). "With this approach, we characterize single-cell production of Ifnb1, Xcl1 and Ccl5 in mouse tumors and identify monocytes and monocyte-derived macrophages as the main producers of type I interferon transcript Ifnb1 consistent across 4 different syngeneic tumor models." (PMID 39372774, 2024). "Taking all these together, our results demonstrate a strong positive association between EP300 mutations, overexpression and stemness/NK marker XCL1 related signatures, suggesting that EP300 may have a role promoting tumours to become a more aggressive subtype in ESCC." (PMID 39419971, 2024). "Local delivery of XCL1 could promote their recruitment in the tumor bed." (PMID 30809220, 2019). "Notably, NK cells produced CCL5 and XCL1, which facilitated cDC1 recruitment to the tumor site." (PMID 31138701, 2019). "Research in murine tumor models has shown that cDC1 infiltration depends on NK cells, which release the chemoattractants CCL5 and XCL1." (PMID 40667699, 2025). "Integration analysis of spatial transcriptome, scRNA-seq, and bulk RNA-seq data further revealed that the potential interactions between XCL1+ CD8+ T cells and NK cells, and XCL1+ CD8+ T cells and myeloid cells, play the key role in anti-tumor immunity." (PMID 41426973, 2025). "In mouse melanoma tumours, NK cells promote cDC1 anti‐tumour functions by enhancing their accumulation in the TME via production of cDC1 chemoattractants CCL5 and XCL1 and cDC growth factor Flt3L." (PMID 40878038, 2025). "The main problem for playing the anti-tumor role of XCL1+ CD8+ T cells is the low expression of XCL1 and key related genes (XCR1 and XCL2) in tumor microenvironment of HCC." (PMID 41426973, 2025). "NK cells secrete cytokines and chemokines, such as CCL5, XCL1, and XCL2, which promote dendritic cell migration into solid tumors, and enhance the anti-tumor activity of CD8+ T cells." (PMID 40657373, 2025). "One subpopulation expressed CD44 + CXCR3 + CXCR4 + PRF1 + and GZM family genes, while the other expressed XCL1 + NCAM1 + GNLY + and KIR family genes, suggesting that these T cells possess a robust capacity to mediate tumor cell apoptosis." (PMID 40411616, 2025). "While the HAS group was enriched in tumor cells and showed a lower infiltration of CD8-CCR7, CD8- CXCL13, CD8-GNLY, FCGR3A NK cells, XCL1 NK cells, plasma cell (PC) and other immune subsets." (PMID 39267750, 2024). "Conversely, other studies have observed that tumor-infiltrating natural killer (NK) cells can recruit cDC1s through production of CCL5 and XC-chemokine ligand 1 (XCL1) and promote their survival with FMS-related tyrosine kinase 3 ligand (FLT3l)." (PMID 38523840, 2024). "Surprisingly, XCL1 and CD160 were predominantly expressed in tumour cells, with a few positive immune cells infiltrated in the stroma." (PMID 39419971, 2024). "Here, we constructed a novel DNA vaccine (XCL1-MS) that expresses XCL1, MUC1 and survivin fusion antigens to target cDC1, aiming to induce a robust CD8+T cell response to inhibit tumor development." (PMID 38339158, 2024). "These replicons were engineered to express cytokines like XCL1, IL-12 or FMS-like tyrosine kinase 3 ligand (Flt3L), or checkpoint inhibitors and demonstrated strong T cell-dependent anti-tumor activity in vivo." (PMID 38425844, 2024). "In MC38 tumor tissues, the relative mRNA expression of CCL5 was significantly decreased in aged mice, while XCL1 showed a moderate decrease." (PMID 38725070, 2024). "NK cells secrete cytokines, such as XCL1, CCL5 and FLT3LG, to stimulate dendritic cell (DC) infiltration into the tumour microenvironment and interact with cytotoxic CD8+ T cells to improve patient responses to immunotherapy." (PMID 38893071, 2024).
tumor (continued). "Some cytokines, including XCL1 and XCL2, were found to be highly expressed specifically in tumour-infiltrating NK cells." (PMID 38893071, 2024). "We found that Xcl1 and Xcr1 that control cDC1 migration were notably upregulated in tumors from hsBCL9z96-treated CT26 tumor-bearing mice." (PMID 38811552, 2024). "Recruitment of cDC1s into the tumor site is also crucial for their anti-tumor activity and depends on the presence of different chemokines in the TME—such as XCL1, XCL2 and CCL5—mainly produced by NK cells." (PMID 37190135, 2023). "NK cells also impact on DC recruitment to the tumor bed through the release of a panel of chemokines, including CCL5, X-C Motif Chemokine Ligand 1 (XCL1), and XCL2." (PMID 37298470, 2023). "Recent studies have found that tumor-infiltrating NK cells and CD8+ T cells activated by IL-15 upregulate the secretion of a chemokine named XCL1." (PMID 37251333, 2023). "PGE2 also prevents NK cells from secreting XCL1 and CCL5, highlighting its function as an immunosuppressive mediator to prevent cDC1s from migrating to the tumor." (PMID 36703982, 2022). "Injecting a virus-based vector expressing XCL1 and soluble Flt3L intratumorally improved tumor control in MC38- and B16-bearing mice through the accumulation of cross-presenting Batf3 DCs in the tumor draining lymph node." (PMID 35626062, 2022). "We also noted that the tumor enriched C5 cells were characterized by the expression of resting NK cells markers, such as AREG, XCL1, and KLRC1, while the C9 cells, which expressed the CX3CR1 and NKG7, were abundant in normal tissues." (PMID 36008393, 2022). "XCL1 had an additional positive effect on antigen uptake by DCs in the TME and antigen transfer to tumor-draining lymph nodes." (PMID 36654820, 2022). "Inside the TME, Prostaglandin E2 (PGE2) inhibits CCL5 and XCL1 production and leads to reduced NK cell viability, highlighting that the TME can interfere with NK cell-mediated anti-tumor functions through multiple mechanisms." (PMID 36372017, 2022). "We found that these 2 types of NK cells expressed tumor-suppressing genes (XCL1 and XCL217 for NK-C1-XCL1, cytotoxic genes for NK-C2-GZMH) in higher proportions in PTs than in LNMTs." (PMID 36357424, 2022). "To explore tumor antigen delivery to human cDC1s, we used an engineered version of XCR1-binding lymphotactin (XCL1), XCL1(CC3)." (PMID 35428705, 2022). "Fluorescence-activated cell sorting (FACS) analysis showed that CCL19, CCL21, and XCL1 boosted the ratios of DCs and T cells in CD45+ leukocytes while CCL3 increased the percentage of CD45+ leukocytes in total cells in MC38 tumor." (PMID 36654820, 2022). "Tumoral overexpression of CCL19, CCL21, and XCL1 significantly increased ratios of total cDCs, cDC1, and cDC2 subtypes among CD45+ leukocytes in the TME, as compared to the empty vector control tumors." (PMID 36654820, 2022). "In conclusion, we produced a recombinant human XCR1 agonist (XCL1(CC3)) and developed a strategy to conjugate it to a poorly soluble epitope of a clinically relevant tumor antigen." (PMID 35428705, 2022). "In a murine model, XCL1 and CCL5 were mainly produced by NK cells and attracted conventional type 1 dendritic cells (cDC1) into the tumor microenvironment." (PMID 35626062, 2022). "These chemokines can be secreted by the tumor itself (e.g., CCL4, CCL5, XCL1) or by other infiltrating immune cells." (PMID 36230990, 2022). "Whereas, Batf3 DCs can be recruited to the tumor bed through the chemokine (C-C motif) ligand 5 (CCL5) and XCL1 (also known as ATAC, lymphotactin, or SCM-1) produced by NK cells." (PMID 35626062, 2022). "Our scRNAseq analysis also shows that the T cell populations activated by neo-aPD1 produces chemotactic factors that recruit DCs (XCL1, XCL2) and additional T cells (CCL5) into the tumor microenvironment." (PMID 34836966, 2021). "For example, NK cells can recruit DCs into tumor microenvironment and enhance the anti-tumor immune activity through secreting CCL5 and XCL1." (PMID 33262461, 2021).
tumor (continued). "In tumor-infiltrate Tregs, we found that IFIT2, CCL3, RBPJ, etc. were upregulated in GC tissues compared to adjacent normal tissues while IGJ, XCL1, XCL2, etc. were downregulated." (PMID 32039830, 2020). "However, tumor moDCs may also develop and function independently of pre-cDC-derived DCs, as already differentiated circulating cDC1s may accumulate in the TME in response to the production of CCL5 and XCL1 by tumor-infiltrating NK cells, CD8+ T cells, and innate lymphoid cells." (PMID 32486257, 2020). "XCR1 (X-C motif chemokine receptor 1) and XCL1 (X-C motif chemokine ligand 1) had been reported to enhance proliferation of antigen-specific CD8+ T cells and their anti-tumor immunity." (PMID 33043022, 2020). "Taken together, chemokines such as XCL1, CCL4, and CCL5 secreted by NK cells and activated T cells within the TME recruit cDC1s into the tumor where they efficiently process antigens and then migrate to lymph nodes while they undergo maturation." (PMID 33679726, 2020). "NK cells also promote recruitment of conventional DC-type 1 (cDCs) in the tumor microenvironment via secreted CCL5 and XCL1 cytokines." (PMID 30974896, 2019). "Elevated COX activity in tumor cells results in production of prostaglandin E2, which reduces NK cell infiltration and thus reduced the cDC1 recruitment factors XCL1 and CCL5 in the tumor microenvironment." (PMID 31849950, 2019). "For instance, Xcl1 or an anti-Xcr1 mAb have been fused to the full OVA protein and tested in antitumor vaccinations, albeit in a tumor prophylaxis setting." (PMID 30863405, 2019). "Similar to Ptgs1/Ptgs2−/− BRAFV600E tumors, B16-OVA tumors (that do not produce PGE2) expressing CCL5 and XCL1 showed increased accumulation of cDC1 within the TME and decreased tumor growth." (PMID 29429633, 2018). "In vitro analysis showed that tumor-derived PGE2 resulted in diminished secretion of CCL5 and XCL1 by NK cells and increased NK cell death." (PMID 29986768, 2018). "Compared with their counterparts in normal lung tissue, tumor-infiltrating CD4+ TRMs exhibited elevated expression of immune checkpoint molecules, indicating a dysfunctional state, accompanied by significantly reduced XCL1 expression." (PMID 41486351, 2026). "Taken together, our spatial transcriptomics analysis supported that the XCL1+ CD8+ T cells could communicate with NK and myeloid cells to play an anti-tumor immunity role in HCC." (PMID 41426973, 2025). "Among them, the chemokine family, including CC (e.g., CCL1, CCL3, CCL5, CCL7, and CCL15), CXC (e.g., CXCL1, CXCL3, CXCL5, and CXCL10), XC (e.g., XCL1 and XCL2), and CX3C (e.g., CX3CL1), plays a pivotal role in tumor development, metastasis, and chemotherapy resistance 30-33." (PMID 40740234, 2025). "The chemokine and receptor profiles of tumor-infiltrating NK1 and NK5 showed increased expression of CCL5, CCL4, XCL1, XCL2, and CXCR3, suggesting that they may be involved in NK tumor homing and activation." (PMID 40315330, 2025). "Additionally, NK cells secrete XCL1 and CCL5, which specifically attract cDC1s, underscoring an NK‐DC interaction that enhances tumor immune surveillance." (PMID 40667699, 2025). "We found that XCL1+ CD8+ T cells could communicate with NK and myeloid cells through CD99 and MIF signaling pathways to regulate the anti-tumor immunity of CD8+ T cell in HCC TME." (PMID 41426973, 2025). "Interestingly, we found that in the C3 immune cluster of ESCC characterised by relatively higher levels of XCL1 and CD160, ~50% of tumours are from the stemness subtype, which presents a significant WNT alteration." (PMID 39419971, 2024). "studies indicated that NK cells can also produce chemokines, C-C-motif ligands such as CCL3, CCL4, CCL5, X-C-motif chemokine ligand 1 (XCL1) and C-X-C-motif chemokine ligand 8 (CXCL8), which attract a variety of immune cells to transformed tissues and inhibit tumor progression." (PMID 36741415, 2022).
tumor (continued). "Additionally, these cells showed reduced levels of Ccl5, which together with XCL1, attracts XCR1+ conventional dendritic cells 1 (cDC1) into the TME, thereby promoting tumor control." (PMID 36372017, 2022). "XCL1 promotes antitumor activity, and XCL1 expression is also significantly related to the number of tumor infiltrating CD8+T cells as well as the expression of PD-L1 in tumor cells." (PMID 35464849, 2022). "Additionally, we found that CD39i treatment increased the proportion of tumor infiltrated cDC1, XCR1 + cDC1 as well as the tumor Xcl1 protein levels in control mice, but not in NK cell absent mice." (PMID 36347860, 2022). "In contrast, cDC1 migrate via XCL1 and CCL5, presumably produced by tumor infiltrating NK-cells." (PMID 36741389, 2022). "After confirming that XCL1(CC3)-LPETGG-FLAG could be modified while retaining XCR1 binding capacity, we set out to generate a construct able to deliver tumor antigens to cDC1s." (PMID 35428705, 2022). "NK cells ́ critical functions to induce an effective tumor immunity depend on a successful crosstalk with conventional dendritic cells (cDC1) and the production of the chemokines CCL5 and XCL1, and that tumor-derived prostaglandin E2 (PGE2) interferes with this reciprocal stimulatory loop." (PMID 34394116, 2021). "Furthermore, XCL1-V21C/V59C strongly induced OVA-specific CD8+ CTLs and protected mice against lethal challenge with OVA-expressing tumor cells." (PMID 34065346, 2021). "In addition, it has recently been reported that activated CD8+ T cells and NK cells secrete XCL1 and attract XCR1-expressing cDC1s to the tumor microenvironment." (PMID 34885241, 2021). "Through immunohistochemistry analysis, we identified XCL1 expression on tumor cells in 13/24 (54%) of MCT-SCCs but not in MCTs." (PMID 32115573, 2020). "Importantly, we detected and validated a new subset of CCL18+ M2 macrophages and a new subset of XCL1+CD8+ T cells that correlated with disease progression and anti-tumor responses, respectively." (PMID 33298893, 2020). "We found that both tumor-infiltrating NK and CD8+ T cells produce XCL1." (PMID 32461349, 2020). "Transcriptomics and proteomics analyses revealed complex effects on the tumor microenvironment triggered by hetIL-15 therapy, including increased levels of IFN-γ and XCL1 with intratumoral accumulation of XCR1+IRF8+CD103+ conventional type 1 dendritic cells (cDC1)." (PMID 32461349, 2020). "XCL1 produced by tumor cells may induce PD1/PD-L1 interaction and dysfunction of CD8-positive T cells in tumor microenvironment." (PMID 32115573, 2020). "In this context, we aimed to target to Xcr1+ DCs tumor antigens in the form of SLP genetically fused or not to the Xcl1 chemokine." (PMID 30863405, 2019). "To be closer to a clinical situation, we wanted to assess the tumor protection capacity of the Xcl1 recombinant proteins in therapeutic vaccinations without OT-1 adoptive cell transfer." (PMID 30863405, 2019). "Importantly, vaccination with Xcl1 fusion proteins did not only elicit a quantitatively higher CTL response, but also a qualitatively increased recruitment and functionality at the tumor site." (PMID 30863405, 2019). "In contrast to CCL5, which acts on the chemokine receptor CCR5 and can promote migration of tumor-promoting immune cells such as macrophages and Treg cells 32, 33, XCL1 acts as a ligand for XCR1 and acts on XCR1+ cDC1s but not on other cells." (PMID 30352680, 2018). "After recruitment, XCL1 further improves the activation and proliferation of CD8 T cells, and these CD8 T cells could produce various cytokines to increase cytotoxic activity against tumor cells." (PMID 41426973, 2025). "Furthermore, trajectory inference revealed that XCL1+ CD8+ T cells probably have strong development ability to other CD8+ T subpopulations, especially for GZMA+ CD8+ T cells, suggesting that probably plays a key role in anti-tumor immunity." (PMID 41426973, 2025).
tumor (continued). "However, following NK cells infusion, there was no change in the relative mRNA expression of CCL5 and XCL1 in the tumor tissues." (PMID 38725070, 2024). "Intense interactions between GZMAhigh NK cells and DCs and between XCL1high NK cells and DCs via XCL1/XCL2-XCR1 and FLT3LG-FLT3 pairs were detected, suggesting that GZMAhigh and XCL1high NK cells may recruit and activate DCs into the tumor site." (PMID 37430270, 2023). "Notably, the C2-CD8 cluster was characterized by low expression of cytokines/chemokines (CCL3, CCL4L2, XCL1, and XCL2), which might hinder infiltration of effector CD8 T/NK cells and DCs into the peritoneum for their anti-tumor functions." (PMID 36788228, 2023). "COX-2/PGE2 can also inhibit the secretion of CCL5 and XCL1 by natural killer (NK) cells and the expression of CCR5 and XCR1 in conventional type 1 dendritic cells (cDC1), which can impair the function of NK cells and the accumulation of cDC1 in the TME, which are responsible for tumor immunity." (PMID 35603146, 2022). "Overall, our results suggest that the establishment of an effective tumor-killing environment composed of favorable cell types, such as DCs, CD8+ memory T-cells, and NK cells, as well as important chemokines, including CCL19, CXCL10, and XCL1 relies on all aspects of the combination therapy." (PMID 36741387, 2022). "Tumor-intrinsic upregulation of COX activity and PGE2 production may be responsible for impaired NK cell recruitment and the consequent reduction of CCL5- and XCL1-mediated intratumoral cDC1 and CTL infiltration." (PMID 32486257, 2020). "In contrast, in mice receiving free OVA SLP + free Xcl1, tumor volumes started to decrease only by day 15 but did not disappear, while in mice receiving only the OVA SLP and CpG, only a delay in tumor growth was obtained but no transient decrease of tumor volumes." (PMID 30863405, 2019). "To investigate whether the two chemokines are necessary for cDC1 recruitment into tumors, we treated WT mice with neutralizing antibodies against CCL5 (αCCL5) and XCL1 (αXCL1) or isotype-matched control antibodies and implanted them with Ptgs1/Ptgs2−/− BRAFV600E tumor cells." (PMID 29429633, 2018). "In addition, these settings also revealed that the ratio between antigen-specific CD8+ T cells and Tregs inside the tumor mass was 4-fold higher in Xcl1 fusion proteins-vaccinated cohorts when compared to mice vaccinated with free OVA SLP with or without free Xcl1." (PMID 30863405, 2019). "Indeed, fully differentiated cDC1 recruited from blood or surrounding tissue might be the predominant origin of intratumoral cDC1s that accumulate in response to XCL1 and CCL5 produced by tumor NK cells because cDC1 precursors express only low levels of transcripts for CCR5 and XCR1." (PMID 30352680, 2018). "In therapeutic tumor vaccination settings, vaccination with the OVA SLP fused or not to Xcl1-Fc fusion proteins enhanced CD8+ T cell responses and delayed B16.OVA tumor growth." (PMID 30863405, 2019). "On this note, it seems intuitive to preferentially target the XCL1/XCL2-XCR1 axis rather than CCL5 to guide cDC1 into tumors, thereby ensuring that CCL5-mediated recruitment of tumor-promoting immune cells such as macrophages or regulatory T cells is avoided." (PMID 29429633, 2018). "Immunohistochemical results suggested that in tumor tissues, CASP8 and SAMSN1 showed high staining, TXNIP showed medium staining, while KLF6 and XCL1 showed negative staining; in normal tissues, KLF6 showed medium staining, CASP8 and SAMSN1 showed low staining, while TXNIP showed negative staining." (PMID 40149637, 2025). "A significant tumor growth delay was obtained in cohorts vaccinated with Xcl1-(OVA SLP)-Fc and OVA SLP + Xcl1-Fc fusion proteins, as compared to mice not receiving Xcl1 (OVA SLP and CpG only), while only a tendency to a higher delay was observed against the OVA SLP + free Xcl1 cohort." (PMID 30863405, 2019).